IL5 (interleukin 5)
Description:
Homodimeric cytokine expressed predominantly by T-lymphocytes and NK cells that plays an important role in the survival, differentiation, and chemotaxis of eosinophils. Also acts on activated and resting B-cells to induce immunoglobulin production, growth, and differentiation (By similarity). Mechanistically, exerts its biological effects through a receptor composed of IL5RA subunit and the cytokine receptor common subunit beta/CSF2RB. Binding to the receptor leads to activation of various kinases including LYN, SYK and JAK2 and thereby propagates signals through the RAS-MAPK and JAK-STAT5 pathways respectively.
Synonyms: IL-5; TRF; EDF
Tractability: Antibody: an approved drug acts on it; UniProt places it where antibodies can reach, with high confidence; its Gene Ontology location is reachable by antibodies, with high confidence; UniProt predicts a signal peptide or a membrane-spanning region. PROTAC: a small molecule that binds it is known.
Target class: Secreted protein
Gene: Protein-coding gene on chromosome 5 (132,541,445 to 132,556,838, reverse strand). Ensembl gene ENSG00000113525.
Subcellular location: Secreted
Pathways (Reactome):
Immune System: Interleukin receptor SHC signaling; Interleukin-3, Interleukin-5 and GM-CSF signaling
Developmental Biology: Differentiation of naive CD4+ T cells to T helper 2 cells (Th2 cells)
Signal Transduction: RAF/MAP kinase cascade
Gene Ontology:
Molecular function: cytokine activity; protein binding; interleukin-5 receptor binding; growth factor activity
Biological process: cell surface receptor signaling pathway via JAK-STAT; interleukin-5-mediated signaling pathway; positive regulation of podosome assembly; positive regulation of receptor signaling pathway via JAK-STAT; inflammatory response; cytokine-mediated signaling pathway; immune response; positive regulation of B cell proliferation; positive regulation of cell population proliferation; positive regulation of eosinophil differentiation; positive regulation of immunoglobulin production; positive regulation of transcription by RNA polymerase II
Cellular component: extracellular region; interleukin-5 receptor complex; plasma membrane
Genetic constraint (gnomAD): Loss-of-function variants: 8 observed, 13.53 expected, observed/expected ratio (o/e) 0.59, 90% interval 0.35 to 1.07. The upper end of that interval is the gene's LOEUF score, 1.07, which puts it in group 4 of 6, group 1 being the genes least tolerant of losing a copy. Missense variants: 132 observed, 137.99 expected, observed/expected ratio (o/e) 0.96, 90% interval 0.83 to 1.11. Synonymous variants: 49 observed, 52.96 expected, observed/expected ratio (o/e) 0.93, 90% interval 0.74 to 1.17.
Homologues: Orthologues: chimpanzee IL5 (100% identical), macaque IL5 (96% identical), chimpanzee IL5 (93% identical), guinea pig IL5 (72% identical), rabbit IL5 (72% identical), mouse Il5 (69% identical), pig IL5 (69% identical), rat Il5 (69% identical), dog IL5 (65% identical).
Diseases named in the same sentence as IL5 in open-access papers:
IL5 is named in the same sentence as 586 diseases in open-access papers, as found by Europe PMC text mining. Sharing a sentence is not in itself a finding about the gene and the disease. The quoted sentences say what the papers report.
asthma (1,528 papers, 2005 to 2026). "This study aimed to evaluate the clinical remission rates and associated factors in patients with severe asthma receiving biologic therapy with either omalizumab (anti-IgE) or mepolizumab (anti-IL-5)." (PMID 41598385, 2026). "IL-4 and IL-5 are largely produced by activated Th2 cells, contributing to humoral immunity and often linked to allergies and asthma." (PMID 41313182, 2026). "IL-5, a key mediator of type 2 inflammation, underlies various diseases, including severe asthma, CRSwNP, EGPA, and HES." (PMID 41556088, 2026). "It is associated with several cytokines, such as IL-4, IL-5, and IgE, and several novel immune agents have also been proposed for this asthma subtype." (PMID 40933990, 2025). "Only recently were ILC2 defined, the importance of the alarmins explored, and the direct association with ILC2, and their IL-5 and IL-13 production, with allergy and asthma determined." (PMID 40821845, 2025). "T2 asthma is linked to atopy and eosinophilic inflammation, which involves cytokines such as IL-4, IL-5, IL-9, and IL-13." (PMID 41318536, 2025). "The link between IL-5 and eosinophilic inflammation has been demonstrated in animal and human asthma experiments, where inhibition of IL-5 with monoclonal antibodies reduced eosinophils caused by allergens or chronic diseases." (PMID 40958130, 2025). "Type 2 immune responses—characterized by high expression of interleukin (IL)-4, IL-5, and IL-13—are associated with asthma featuring elevated blood or sputum eosinophil counts, serum immunoglobulin E (IgE) levels, and fractional exhaled nitric oxide (FeNO)." (PMID 41584312, 2025). "Higher levels of IL-5 and eosinophils are typically linked with more severe asthma and frequent exacerbations." (PMID 40564060, 2025). "IL-5 and IL-13 represent type-2-mediated eosinophilic inflammation, which has been implicated in airway remodeling in long-standing asthma." (PMID 41440978, 2025). "T helper cell 2, i.e., Type 2 (T2) high asthma and CRSwNP are linked to eosinophils and cytokines, interleukin (IL)-4, IL-5, IL-13, while Type 2 low endotype involves Th17 pathways and neutrophilic inflammation." (PMID 41213931, 2025). "By targeting immunoglobulin E (IgE), thymic stromal lymphopoietin (TSLP), and specific cytokines such as IL-5, IL-4, and IL-13, biologics offer more precise and personalized treatment in patients with severe asthma and associated comorbidities." (PMID 41156259, 2025). "There is thus, a close inflammatory association between asthma and CRSwNP, in which eosinophils and IL-5 play a central role." (PMID 39554605, 2025). "The most common asthma variant in children, T2-high asthma, is characterized by atopy, eosinophilic inflammation, elevated Th2 cytokines (IL-4, IL-5, and IL-13), and leukocyte recruitment driven by CD4 + T-cells, mast cells, and eosinophils." (PMID 40806181, 2025). "Recent advances in biomarker research, driven by biological therapies, have identified various CRS clusters with distinct inflammatory profiles, predominantly Th2 high IL-5 levels are associated with a nasal polyp phenotype and increased asthma prevalence." (PMID 41213931, 2025). "Cytokine activity is closely associated with asthma, as cytokines like IL-4, IL-5, and IL-13 can promote mucus overproduction and bronchial hyperresponsiveness, which are symptoms of asthma." (PMID 40266878, 2025). "Previous studies have shown that PI3K inhibitors suppress pathological features associated with asthma, including chemokine secretion by activated eosinophils, increased levels of IL-5 and IL-13 in the bronchi, and eosinophil infiltration in lung tissue." (PMID 39940325, 2025). "Th2 immune responses are characterized by the increased production of IL-4, IL-5, and IL-13, and have been associated with RV infection in asthma." (PMID 39941446, 2025).
asthma (continued). "All the patients treated with anti-IL5/5R had a diagnosis of asthma associated with CRSwNP, whereas in the groups treated with anti-IgE, 8 out of 9 patients had both asthma and CRSwNP, 1 was not asthmatic." (PMID 40151546, 2025). "Th2 cells are pathogenic in asthma because they produce high amounts of the prototypical type 2 cytokines IL-4, IL-5, IL-9, and IL-13." (PMID 41145900, 2025). "Among the highly upregulated proteins, IL-13 strongly correlated with IL-5, both linked to Th2-type immune responses and associated with allergic inflammation, asthma, and other viral lung infections like influenza and RSV (respiratory syncytial virus)." (PMID 40557167, 2025). "Asthma is a persistent inflammatory condition of the airways linked to type 2 cytokines, such as IL-4, IL-5, and IL-13." (PMID 40558541, 2025). "Through the inhibition of IL-5, mepolizumab reduces the eosinophil count in the blood and tissues, contributing to better asthma control and reducing the risk of exacerbations." (PMID 40003269, 2025). "Elevated eosinophil levels (≥150–300 cells/μL) are predictive of good response to anti-IL-5 therapies (mepolizumab, reslizumab, benralizumab) and are associated with increased exacerbation risk in severe asthma." (PMID 40564060, 2025). "Previous research has indicated that increased levels of IL-5, IL-6, and IL-8 are associated with heightened air pollution, potentially contributing to asthma, cardiovascular diseases, and metabolic risks." (PMID 40611827, 2025). "Higher baseline BEC was also associated with lower probability of uncontrolled asthma (OR 0.392; p=0.001) post-biologic for anti-IL5/5R." (PMID 38711495, 2024). "In type 2-high asthma, type 2 inflammation is present with its associated cytokines IL-4, IL-5, and IL-13, high levels of blood and/or sputum eosinophils, and elevated FeNO." (PMID 39765793, 2024). "The lung damage caused by eosinophil degranulation generated by IL-5 in a mouse model of asthma was shown to be greatly reduced in IL-5−/− mice." (PMID 38535313, 2024). "It binds to IL-5 and prevents IL-5 from interacting with IL-5Rα on eosinophils, which reduces eosinophil count and risk of asthma exacerbations." (PMID 38493955, 2024). "For instance, eosinophilic airway inflammation associated with TH2 cytokines (IL-4, IL-5, and IL-13) and/or Ig E is an underlying pathological mechanism in both chronic rhinosinusitis with nasal polyps and asthma." (PMID 38919942, 2024). "For asthma-associated cytokine secretion, IL-5 is primarily a T cell-derived cytokine, which is particularly important for the activation and survival of eosinophils." (PMID 38674852, 2024). "The sensitised mice exhibited an increased expression of the Th2-like and asthma-associated cytokines, IL-4, IL-5, and IL-13, as well as mRNA encoding for pro-inflammatory TNF-α and the Th1 cytokine IFN-γ." (PMID 38765484, 2024). "Th2 cells promote airway inflammation by production of a range of cytokines including IL-4, IL-5, IL-9, IL-13 and IL-25, which together are responsible for the development of hallmark features of asthma." (PMID 39598682, 2024). "Recent advances in understanding asthma pathogenesis have made it clear that various cytokines, in addition to the atopy-associated Th2 cytokines (IL-4, IL-5, and IL-13), play crucial roles in the induction and regulation of airway inflammation." (PMID 39902293, 2024). "Briefly, as the induction of asthma is a complex topic, Th2-high asthma represents the mechanism of IL-4, IL-5, and IL-13 associated asthma, which induces roughly 50% of mild-to-moderate asthma and the majority of severe asthma inflammation." (PMID 39239645, 2024). "There is increasing evidence that asthma is associated with persistent low-grade inflammation, indicated by higher levels of inflammatory markers such as IL-4, IL-5, and IL-13." (PMID 39372270, 2024).
asthma (continued). "Studies have revealed that estrogen can enhance the production of type 2 cytokines, such as interleukin-4 (IL-4) and interleukin-5 (IL-5), which play critical roles in promoting airway inflammation and allergic responses associated with asthma." (PMID 39026347, 2024). "This disease has mainly been associated with Th2 cell cytokines, i.e., IL-4, IL-5, and IL-13, however recent developments have led to a terminology of Th2-high and Th2-low asthma." (PMID 39239645, 2024). "Asthma was associated with the increased expression of pro-inflammatory cytokines, including IL-2, IL-5, IL-13, IL-17A, IL-22, IL-33, and TNF-α, and reduced levels of anti-inflammatory cytokine, IL-10 and adipokine, leptin in the circulation." (PMID 39902293, 2024). "The pathogenesis of asthma has been linked to an imbalance between Th2 and Th1 cells, resulting in increased levels of interleukin (IL)-4, IL-5, and IL-13 and decreased levels of interferon (IFN)-γ." (PMID 39539452, 2024). "Two antibodies against IL-5 and one against IL-5Rα are now approved treatments for severe asthma associated with persistent eosinophilia, in addition to glucocorticoid therapy, reducing annualized exacerbation rates and moderately improving lung function." (PMID 40047886, 2024). "Greater baseline BEC was also associated with a lower probability of uncontrolled asthma post-biologic, but only for patients treated with anti-IL5/5R therapy." (PMID 38711495, 2024). "Elevated levels of IL-13, IL-4, and IL-5 are particularly associated with asthma, contributing to airway hyperresponsiveness, eosinophil recruitment, and mucus production." (PMID 39902079, 2024). "Type 2 cytokines (e.g., IL-13, IL-5, and IL-4) facilitate asthma’s hallmark characteristics (e.g., susceptibility to exacerbations, IgE production, AHR, IgE production, mucus hypersecretion, and eosinophilia)." (PMID 38245791, 2024). "Th2 cells are best known for producing IL-4, IL-5, and IL-13 and are associated with host defenses against parasites and involvement in allergies and atopic diseases such as asthma." (PMID 39481080, 2024). "Higher concentrations of IL-5 were detected in the induced sputum of patients with acute exacerbations of asthma, and IL-5 mRNA expression was associated with clinical severity of asthma." (PMID 39175819, 2024). "IL-5 and IL-4/IL-13 are considered the key drivers of type 2 pathways underlying eosinophilic airway inflammation in asthma." (PMID 37108417, 2023). "Recently, the use of anti-IL-5 (IL, interleukin) antibody therapies for severe asthma has been associated with the onset of rheumatoid arthritis (RA) and other inflammatory rheumatological disease." (PMID 38114196, 2023). "Studies in asthmatic animals show that autophagy is associated with a severe eosinophil phenotype and that anti-IL-5 has a beneficial effect on asthma treatment by reducing autophagy." (PMID 37090692, 2023). "Alongside the canonical cytokines IL-4, IL-5, and IL-13, it is also clear that human Th2 cells can take on characteristics normally associated with other Th subsets in asthma." (PMID 37163370, 2023). "Both activated Th2 cells and ILC2s produce large amounts of the type-2 cytokines IL-4, IL-5, IL-9, and IL-13, which in turn trigger hallmark asthma symptoms." (PMID 37612281, 2023). "Particularly, IL-5 produced by Th2 has been long associated with several allergic diseases including rhinitis and asthma." (PMID 37664635, 2023). "In patients with asthma, levels of type-2 instructional cytokines (IL-33 and IL-25) and effector cytokines (IL-4, IL-5, and IL-13) are elevated in the airway mucosa, associated with impaired antiviral immunity." (PMID 37174726, 2023). "Interleukin (IL)-5 is central in initiating the eosinophilic airway inflammation associated with severe asthma." (PMID 38259298, 2023).
asthma (continued). "The metabolism of arachidonic acid can produce cysteinyl leukotrienes, which is overexpressed in asthma patients and has recently been linked to the production of IL-4, IL-5, and IL-13 by binding ILC2 and Th2 cells." (PMID 37680636, 2023). "Targeting IL-5 has become a well-established therapy for patients with uncontrolled severe asthma caused predominantly by T2 inflammation with eosinophilia." (PMID 37199256, 2023). "The association of T2 asthma with nasal polyposis has been considered a factor predicting response to anti-IL-5 antibodies in asthma." (PMID 37509606, 2023). "Functionally, Th2A cells have increased expression of IL-5 and IL-9 but a similar expression of IL-4 and IL-13 compared with conventional Th2 cells, aligning with the asthma-associated cluster identified transcriptionally." (PMID 37163370, 2023). "There are other miRNAs associated with the pathology of asthma and allergies, such as miR-21, which targets IL-12p35 in steroid-resistant asthma; miR-1248, which targets IL-5; and miR-15a, which inhibits VEGFA in CD4 + cells." (PMID 37605155, 2023). "Smirnova S.V., Smolnikova M.V., Konopleva O.S. Polymorphism ofgenes (IL4, IL5) as a genetic predisposition to asthma in children.Eur." (PMID 37465198, 2023). "Both IL-5 and IL-13 have important roles in lung inflammation associated with asthma, COPD, and chronic rhinitis." (PMID 37107767, 2023). "CRSwNP and asthma share similar pathophysiology and are associated with eosinophilic infiltration and Th2 cytokines such as interleukin-4, interleukin-5, and interleukin-13 (IL-4, IL-5, and IL-13) as well as high levels of local immunoglobulin-E (IgE)." (PMID 37674852, 2023). "Our results are in line with those of a previous study showing that higher FEV1 and shorter asthma duration were associated with super responders after 2 years of anti-IL-5 treatment." (PMID 37109237, 2023). "IL-5 is frequently associated with eosinophils and asthma but was also shown in some animal studies to polarise monocytes towards an anti-inflammatory phenotype." (PMID 37761018, 2023). "Exacerbation of asthma is associated with the elevated expression of IL-5, IL-4, IFN-γ, IL-12 p40, eosinophil chemokine-1, and TGF-β mRNA in the bronchial tubes." (PMID 35878202, 2022). "Here we describe a case of EGE associated with asthma that was maintained in steroid-free remission following treatment with mepolizumab, an anti–IL-5 antibody." (PMID 39132061, 2022). "Second, it should be noted that eight patients were receiving anti-IL5 or anti-IL5R therapy for associated asthma." (PMID 36248793, 2022). "This discovery was followed by more biological agents targeting key inflammatory nodes in the chronic inflammation underlying asthma, such as IL-5, IL-5R, IL-13 and IL-4R." (PMID 36561741, 2022). "Seys and colleagues evaluated sputum cytokine mRNA expression in an unselected group of adults with stable asthma, and demonstrated that higher levels of IL-5, IL-17A and IL-25 in the airways were associated with uncontrolled asthma and worse lung function." (PMID 35546400, 2022). "Asthma has long been considered as a Th2-associated inflammatory disease, with IL-4, IL-5, and IL-13 as the key cytokines and eosinophilic infiltrates in the airways." (PMID 35408882, 2022). "To assess the function of IL-5-anchored CCAR-T cells in the murine asthma models, we designed murine variants based on mIL-5-anchored CCAR-T cells or CCAR-Jurkat cells specific for murine IL-5Rα (mIL-5Rα)." (PMID 35973984, 2022). "Exuberant production of IL‐4, IL‐5, and IL‐13 leads to asthma features with the accumulation of type 2‐associated cells, such as eosinophils, in lung tissue." (PMID 35758054, 2022). "It has been well documented that type 2 cytokines IL-5 and IL-13 are implicated in the pathogenesis of the eosinophil-rich airway inflammation, which typically characterizes asthma." (PMID 35524325, 2022).